PIN1 (peptidylprolyl cis/trans isomerase, NIMA-interacting 1)
Diseases named in the same sentence as PIN1 in open-access papers (continued):
Sharing a sentence is not in itself a finding about the gene and the disease.
Alzheimer disease (60 papers, 2009 to 2026). A progressive, neurodegenerative disease characterized by loss of function and death of nerve cells in several areas of the brain leading to loss of cognitive function such as memory and language. "Of interest, the irreversible oxidation of human PIN1 was associated with various pathologies as mild cognitive impairment or Alzheimer’s disease and induces a decrease of reactivity and mislocalization impairing the physiological function of the protein." (PMID 34975936, 2021). "Downregulation of Pin1 in brain usually causes Alzheimer’s disease, while Pin1 is frequently overexpressed and/or overactivated in diverse cancers, including leukemia, prostate cancer, and hepatocellular carcinoma (HCC)." (PMID 33024085, 2020). "For instance, deletion or mutation of Pin1 can induce Alzheimer’s disease-like pathological changes in mice." (PMID 31888570, 2019). "While overexpression of Pin1 is implicated in cancer, Pin1 typically protects against tauopathy and plaque formation that leads to Alzheimer’s disease (AD) neurodegeneration." (PMID 31861908, 2019). "Specifically, Pin1 overexpression or amplification is highly correlated with cancer progression and metastasis while Pin1 loss is seen in evolving Alzheimer Disease." (PMID 28971096, 2017). "The PIN1 promoter polymorphism (−842 G>C) was first identified in a study of Alzheimer’s disease, which revealed that the variant −842C allele was associated with an increased risk of Alzheimer’s disease." (PMID 25120724, 2014). "Accordingly, PIN1 has been implicated in the etiology of a large number of pathologic processes including cancer and Alzheimer’s disease." (PMID 23675491, 2013). "The gene encoding PIN1 maps to chromosome 19p13.2, a region associated with late-onset Alzheimer's disease (LOAD)." (PMID 19909517, 2009). "Peptidyl-prolyl isomerase, NIMA-interacting 1 (PIN1) plays a significant role in the brain and is implicated in numerous cellular processes related to Alzheimer's disease (AD) and other neurodegenerative conditions." (PMID 19909517, 2009). "Pin1, a cis-trans prolyl isomerase has recently been implicated in Alzheimer's Disease progression." (PMID 42186247, 2026). "This indicates that Pin1 deficiency is a risk factor for Alzheimer’s disease, and Pin1 may work in the direction of disease suppression." (PMID 36393854, 2022). "Interestingly, an inverse association has been noted between cancer and Alzheimer’s Disease (AD) concerning PIN1 regulation of HIF-1α." (PMID 33383924, 2020). "In addition, older Pin1 KO mice show both a behavior disorder and tau accumulation in the brain, indicating Pin1 deficiency to be a risk factor for Alzheimer’s disease." (PMID 27618008, 2016). "Because regulating these protein functions by Pin1 is involved in diverse physiological and pathological processes, Pin1 deregulation is implicated in a number of diseases, including aging and age-related diseases, such as Alzheimer disease and cancer." (PMID 24899581, 2014). "For example, DHCR24 and PIN1 are associated with Alzheimer’s disease." (PMID 24170811, 2014). "In contrast, Pin1 attenuation in neurodegenerative diseases has been long well established, with Pin1 being most famously known to suppress Alzheimer’s Disease (AD) by regulating tau and amyloid precursor protein turnover and degradation." (PMID 38727267, 2024). "For example, Pin1 KO mice reportedly develop Alzheimer disease because Pin1 binds to and promotes the degradation of Tau protein." (PMID 37240193, 2023). "Pin1 plays a pivotal role in protection against age-dependent neurodegeneration, and an essential role in preventing tau-related and Aβ pathologies in Alzheimer’s disease." (PMID 35433695, 2022). "Pin1 has been reported to be involved in cancer development, obesity, aging, and Alzheimer’s disease and has been shown to promote the growth of several viruses including SARS-CoV-2." (PMID 36393854, 2022).
Alzheimer disease (continued). "Disruption in the balance of Pin1 activation can lead to diseases, including cancer and Alzheimer’s disease." (PMID 36497033, 2022). "For example, Pin1 interacts with and promotes the degradation of tau, advantageously contributing to protection from Alzheimer disease." (PMID 34067858, 2021). "Pin1 involvement has been identified in numerous biological processes related to pathological conditions, including cancer, inflammation, Alzheimer’s disease, aging, asthma and microbial infection." (PMID 34067858, 2021). "In other studies, downregulation of Pin1 expression was found to increase the likelihood of developing Alzheimer's disease (AD), and low expression of Pin1 was found in patients with AD 74, 78-80." (PMID 33537091, 2021). "In particular, Pin1 deregulation including PTMs is directly involved in an increasing number of pathological conditions, notably premature aging, cancer and Alzheimer’s disease (AD)." (PMID 32195254, 2020). "Although Pin1 is tightly regulated under physiological conditions, deregulation of Pin1 PTMs contributes to the development of human diseases including cancer and Alzheimer’s disease (AD)." (PMID 32195254, 2020). "The disordered PIN1 expression and/or activity is related to various diseases, such as Alzheimer’s disease and cancer." (PMID 32703934, 2020). "Since the identification of the importance of human peptidyl-prolyl cis/trans isomerase Pin1 in Alzheimer’s disease through the modulation of Tau protein, Pin1 and juglone have gained considerable attention." (PMID 30959841, 2019). "Pin1 has previously been found to be oxidized in the hippocampus of Alzheimer’s disease samples, and the activity in this oxidized Pin1 is reduced." (PMID 31861908, 2019). "Pin1, a polypeptide proline isomerase parvulin, plays a key role in Alzheimer’s disease (AD), common tumors and cancers." (PMID 31182777, 2019). "Pin1 has been recognized as being involved in the pathogenesis of several diseases, including cancers and Alzheimer’s disease." (PMID 31367234, 2019). "Tau’s binding factor Pin1, a mitotic regulator overexpressed in cancer and depleted in Alzheimer’s disease (AD), also plays a role in the activation of nuclear deadenylation." (PMID 31749682, 2019). "Among those regulatory networks, a novel prolyl isomerase Pin1 has drawn much attention about its protective effects against neurodegeneration especially Alzheimer's disease (Liou, Sun, Ryo, Zhou, & Yu, 2003)." (PMID 29992725, 2018). "For example, decreased activity of tumor suppressor proteins and overexpression of Pin1 (peptidyl-prolyl cis-trans isomerase, NIMA-interacting 1) are associated both with cancer and with a lower risk of Alzheimer’s disease." (PMID 28225789, 2017). "Several studies have examined the roles of Pin1 in the pathogenesis of cancers and Alzheimer’s disease." (PMID 27618008, 2016). "Amyloid beta enhances ROS generation from mitochondria during respiration, such that Pin1 dysregulation induces the accumulation of amyloid beta and a switch to oxidative phosphorylation, leading to Alzheimer’s disease." (PMID 27618008, 2016). "Pin1 has also been targeted in the treatment of Alzheimer’s disease, asthma, and a number of cancers." (PMID 25992900, 2015). "Pin1 is the most well characterized parvulin and is a drug target for treatment of cancer, Alzheimers disease, asthma, and inflammation." (PMID 25992900, 2015). "Despite the huge amount of data accumulated so far, much attention has been devoted to the roles of Pin1 played in ageing, cancer and Alzheimer disease." (PMID 23750710, 2013). "The role of polymorphism affecting the AP-4 binding has been assessed in Pin1 promoter with relation to Alzheimer's disease, where the role of AP-4 as a transcriptional repressor has been reported in the context of G to C base exchange." (PMID 22509293, 2012).
Alzheimer disease (continued). "Overexpression of Pin1, a member of the parvulin family of immunophilins, reduces Aβ and knockout of Pin1 increases Aβ production in Alzheimer's disease brains, through the isomerization of the cytoplasmic domain of APP at a phosphorylated Thr668/Pro motif." (PMID 20084280, 2010). "In Alzheimer's disease PIN1 depletion was related to exacerbated tau hyperphosphorylation, generation of NFT and neurotoxic Aβ and subsequent amyloid plaque formation." (PMID 19909517, 2009). "Similarly, post-translational modifications to Pin1 itself can regulate its activity, with the dysregulation of Pin1 PTMs contributing to the pathogenesis of cancer and Alzheimer’s Disease, as reviewed in detail by Chen and his colleagues." (PMID 38727267, 2024). "The prolyl isomerase Pin1 isomerizes cis P-tau to inhibit the development of oligomers, tangles and neurodegeneration in multiple neurodegenerative diseases such as Alzheimer’s disease, traumatic brain injury, vascular contribution to cognitive impairment and dementia (VCID) and preeclampsia (PE)." (PMID 38628595, 2024). "Several studies have shown that PIN1 activity is decreased in the hippocampus of Alzheimer’s disease (AD) patients, which means that this protein plays important roles in the neuronal cell death pathway, in turn suggesting that PIN1 has a neuroprotective role in AD." (PMID 39457664, 2024). "Thus, Pin1 plays an important but opposite role in the pathogenesis of Alzheimer’s disease and many human cancers." (PMID 36829834, 2023). "Pin1 plays an important role in cancer, Alzheimer’s disease, and autoimmune diseases." (PMID 33717117, 2021). "Mis-regulation of Pin1 plays an important role in a growing number of pathological conditions including Alzheimer disease (AD), where it may protect against age-dependent neurodegeneration." (PMID 32218435, 2020). "Pin1 function was shown to be inhibited in humans with Alzheimer ́s disease." (PMID 28426725, 2017). "Moreover, Pin1 overexpression in postnatal neurons in vivo protects against neurodegeneration in a mouse model for Alzheimer ́s disease." (PMID 28426725, 2017). "Detailed molecular analyses in mice and cells led to the findings that in Alzheimer’s disease Pin1 regulates amyloid precursor protein (APP) processing and amyloid-beta production while it is required for Tau dephosphorylation and correct neurofibrillary organization." (PMID 27199664, 2016). "In Alzheimer’s disease Pin1 participates in APP processing and neurofibrillary tangle formation." (PMID 27199664, 2016). "In addition to its involvement in cancer and stress response, Pin1 has been shown to be a critical regulator of dendritic Glu responses and of neurodegeneration in Alzheimer disease." (PMID 25899010, 2015). "Excellent comprehensive reviews covering the function of Pin1 in mitosis, Alzheimer disease, immune response, proliferation control, and cancer biology have been published recently and are recommended to those readers interested in obtaining a global view on Pin1 function." (PMID 24982848, 2014). "As decreased PIN1 level was previously observed in brains of Alzheimer's disease patients, it raises the possibility that identified variant could exert more profound effects in the brain." (PMID 19909517, 2009). "The peptidyl‐prolyl cis/trans isomerase, Pin1, has a protective role in age‐related neurodegeneration by targeting different phosphorylation sites of tau and the key proteins required to produce Amyloid‐β, which are the well‐known molecular signatures of Alzheimer's disease (AD) neuropathology." (PMID 36184817, 2023). "Moreover, Pin1 function is inhibited in human central nervous system (CNS) disorders, including Alzheimer’s disease, Parkinson’s disease and schizophrenia, by multiple mechanisms, which supports the idea that it is an essential protective gene in the nervous system." (PMID 36304997, 2022).
Alzheimer disease (continued). "These Pin1 depletion effects may be due to decreased phosphoprotein interactions, as Pin1 normally interacts with many pro-mitotic phosphoproteins, contributing to disorders like Alzheimer’s disease and cancer." (PMID 35681549, 2022). "Notably, juglone is an inhibitor of Pin1 (peptidyl-prolyl cis/trans isomerase) that could regulate phosphorylation of Tau, implicating potential effects of juglone in Alzheimer’s disease." (PMID 30959841, 2019). "Therefore, we speculate that Pin1 might play an important role in memory via Ca2+ signal pathways as well as neurological diseases like tauopathy and Alzheimer’s disease." (PMID 30532705, 2018). "However, the relationship between Pin1 and Alzheimer’s disease remains unclear." (PMID 30532705, 2018).
hepatocellular carcinoma (45 papers, 2007 to 2026). A malignant tumor that arises from hepatocytes. "MiR-140-5p is also identified as a potential negative regulator of Pin1 expression by directly binding to the 3′-UTR of Pin1 mRNA, inhibiting Pin1 translation in hepatocellular carcinoma." (PMID 32296699, 2020). "In human hepatocellular carcinoma cells, Pin1 binds to p‐NF‐κB‐p65 (Thr254) and stimulates its phosphorylation at Ser276, which is followed by translocation of activated NF‐κB into the nucleus." (PMID 32347623, 2020). "API-1, a small molecule targeting the PPIase domain of Pin1, suppresses the proliferation and migration of hepatocellular carcinoma cells." (PMID 31884567, 2020). "Recent data also involve PIN1 in the regulation of microRNA biogenesis since it affects their nuclear-cytoplasmic shuttling in hepatocellular carcinoma." (PMID 30873382, 2019). "Several studies including those from our group have demonstrated that PIN1 over-expression results in increased cell proliferation in hepatocellular carcinoma (HCC) cells." (PMID 30534074, 2018). "The degree of PIN1 expression has been reported to increase in various types of cancer, including human prostate, breast and lung cancer and hepatocellular carcinoma." (PMID 24179535, 2013). "Knocking out Pin1 was found to significantly inhibit the expression of phosphorylated T254 and S276 in p65, leading to a reduction in NF-κB activity in HepG2 cells, which, in turn, inhibits the progression of hepatocellular carcinoma (HCC)." (PMID 39050887, 2024). "Pin1-mediated β-catenin accumulation occurs in about 70% of hepatocellular carcinoma." (PMID 36829834, 2023). "Pin1 promotes cell proliferation by upregulating cyclins in hepatocellular carcinoma cells." (PMID 32347623, 2020). "All-trans retinoic acid (ATRA) is potent PIN1 inhibitor in hepatocellular carcinoma (Liao X. -H." (PMID 32258027, 2020). "Yang and collogues developed an improved, controlled-release formulation of ATRA (ATRA-PLLA microparticles) that demonstrated selectivity for Pin1 inhibition and improved anti-cancer efficacy in xenografts of hepatocellular carcinoma, a cancer that is enhanced by Pin1." (PMID 33322239, 2020). "We previously demonstrated that XPO5 was phosphorylated by ERK kinase and subsequently underwent conformation change by the peptidyl‐prolyl isomerase Pin1, leading to the reduced miRNA expression in hepatocellular carcinoma (HCC)." (PMID 35441157, 2022). "Moreover, this impaired miRNA biogenesis in hepatocellular carcinoma could be restored by novel Pin1 inhibitors and their formulations, giving new insight into the therapy of liver cancer." (PMID 32296699, 2020). "In addition, several studies have demonstrated that small non-coding microRNAs (miRNAs), including miR-200b in breast tumor, miR-296-5p in prostate cancer, miR-874-3p and miR-140-5p in hepatocellular carcinoma, and miR-370 in esophageal squamous cell carcinoma, negatively regulate Pin1 expression." (PMID 31884567, 2020). "Additionally, NF-κB is also triggered by Pin1 to promote angiogenesis in hepatocellular carcinoma." (PMID 32296699, 2020).
hepatocellular carcinoma (continued). "Pin1 binds to the ERK-mediated phosphorylated XPO5 in hepatocellular carcinoma (HCC) and changes XPO5’s conformation through cis-trans isomerization, leading to the retention of XPO5 in the nucleus and the impaired nuclear export of pre-miRNAs." (PMID 32266261, 2020). "Inhibition of Pin1 reverses regorafenib resistance in hepatocellular carcinoma (HCC) with reducing EMT, migration and metastasis." (PMID 32258027, 2020). "In addition, it is clear that Pin1 inhibition has a marked effect on the suppression of carcinogenesis, and may exert a strong effect against hepatocellular carcinoma development." (PMID 31795496, 2019). "PIN1 overexpression has also been shown to up-regulate cyclin D1 and β-catenin in hepatocellular carcinomas (HCC)." (PMID 27258148, 2016). "Taken together, these observations highlight the importance of Pin1 in NASH development with lipid accumulation, which was confirmed through our experiments using both human clinical samples and cultured hepatoma cell lines." (PMID 37240193, 2023). "In this article, we found that endogenous PIN1 and PIN4 were upregulated in selected hepatocellular carcinoma (HCC) cell lines." (PMID 36760500, 2023). "This suggests that Pin1 and HBx promote the growth of hepatocellular carcinoma (HCC)." (PMID 36393854, 2022). "Pin1 blocks nucleus-to-cytoplasm export of XPO5 phosphorylated by ERK kinase, decreasing mature miRNA biogenesis in hepatocellular carcinoma." (PMID 32296699, 2020). "Indeed, PIN1 over-expression has been found in many cancers, including hepatocellular carcinoma (HCC)." (PMID 32010690, 2019). "PIN1 is a peptidyl-prolyl cis/trans isomerase (PPIase) that regulates multiple signaling pathways to control cell fate and is found to be over-expressed in cancers, including hepatocellular carcinoma (HCC)." (PMID 28076852, 2017). "Over-expression of PIN1 is found in many cancers, including hepatocellular carcinoma (HCC)." (PMID 28076852, 2017). "Similarly, Pin1 levels decrease following cadmium exposure in human hepatoma cells (HepG2) with an IC50 ≥ 6 μΜ, and the inhibition of Pin1 induces autophagy, likely through the upregulation of p-Ser-GSK3αβ." (PMID 38711994, 2024). "Overexpression of HBx and Pin1 in the non-tumorigenic human hepatoma cell line MIHA was found to result in the formation of large tumors in an animal transplantation model." (PMID 36393854, 2022). "Importantly, XPO5 phosphorylation by ERK kinase and its cis/trans isomerization by the prolyl isomerase Pin1 impair XPO5′s nucleo-to-cytoplasmic transport ability of pre-miRNAs, leading to downregulation of mature miRNAs in hepatocellular carcinoma." (PMID 29723684, 2018). "Pin1 has been implicated in colorectal cancer (β-catenin), breast cancer (Cyclin D, AP-1, Akt, centrosome duplication, Notch1), prostate cancer (TRK-fused gene [TFG]), glioblastoma (NF-κB), hepatocellular carcinoma (HCC, p70S6K, β-catenin) and acute myeloid leukemia (AML, AP-1)." (PMID 25588053, 2015). "PIN1 directed NF-κB activation regulates the proliferation of AML, endometrial carcinoma, glioblastoma, and hepatocellular carcinoma (HCC)." (PMID 32258027, 2020). "In terms of targeting FBXW7 itself, the downregulation of prolyl isomerase Pin1 contributes to upregulation of FBXW7 and ensuing destruction of MCL-1, which potentiates the toxicity of sorafenib to prevent cell proliferation and induce apoptosis in hepatocellular carcinoma (HCC)." (PMID 35515121, 2022). "We examined whether or not Pin1 is upregulated, as in NASH biopsy samples, in hepatoma cells with lipid accumulation." (PMID 37240193, 2023).